RPL28P1 (ribosomal protein L28 pseudogene 1)
Synonyms: bcm2489
Gene: Processed pseudogene on chromosome 3 (170,653,846 to 170,654,259, reverse strand). Ensembl gene ENSG00000213174.
Diseases named in the same sentence as RPL28P1 in open-access papers:
RPL28P1 is named in the same sentence as 1 disease in open-access papers, as found by Europe PMC text mining. Sharing a sentence is not in itself a finding about the gene and the disease.
RPL28P1 shares sentences with these, for which no sentence is quoted: ovarian carcinoma (2 papers).